GLUL (glutamate-ammonia ligase)
Diseases named in the same sentence as GLUL in open-access papers (continued):
Sharing a sentence is not in itself a finding about the gene and the disease.
Alzheimer disease (8 papers, 2011 to 2025). A progressive, neurodegenerative disease characterized by loss of function and death of nerve cells in several areas of the brain leading to loss of cognitive function such as memory and language. "We found that glutamate-ammonia ligase (GLUL) is uniquely upregulated in skeletal muscle of prion-infected mice and humans, but not in amyotrophic lateral sclerosis (ALS), Alzheimer’s disease (AD), or dementia with Lewy bodies (DLB)." (PMID 39259763, 2024).
glaucoma (8 papers, 2011 to 2024). Increased pressure in the eyeball due to obstruction of the outflow of aqueous humor. "Glutamine synthase (Gene name: GLUL), a retinal Müller cell marker, was found as an oxidation target protein in a glaucoma rat model and was shown to be up-regulated in retinal rat Müller cells by hypertension." (PMID 31470587, 2019).
Obesity (8 papers, 2020 to 2025). Accumulation of substantial excess body fat. "Circulating glutamate is also associated with excess abdominal adipose tissue in obesity, which is potentially related to expression of the GLUL gene (encoding glutamate-ammonia ligase) and inflammatory genes in adipose tissue." (PMID 38094040, 2023). "Attenuated WAT glutamine levels in obesity were linked to reduced glutamine synthetase (GLUL) expression in several cell types although the reduction was most prominent in adipocytes." (PMID 33043853, 2020). "The expression of glutamine‐metabolizing proteins—such as glutamine synthetase (GLUL) and glutaminase (GLS)—is altered in white adipose tissue from individuals with obesity and is normalized after bariatric surgery." (PMID 40289598, 2025). "Taken together, CD36, GLUL, COL4A2, and ACACB were considered as core genes in human adipose tissue with obesity or T2DM." (PMID 34085602, 2021). "Taken together, CD36, COL4A2, GLUL, and ACACB were considered as core genes closely related to obesity and T2DM." (PMID 34085602, 2021). "We anticipate identifying the genes closely related to obesity and T2DM and further investigate their relationship with the CD36, COL4A2, GLUL, and ACACB as they may be target genes for future therapies." (PMID 34085602, 2021).
liver disease (7 papers, 2013 to 2024). "In an individual without liver disease, the rate of ammonia formation for the first 12.9 s of the simulation was 0.55 μmoles per second, but this rate increased to 0.83 μmoles per second when GLUL activity was inactivated." (PMID 31366360, 2019).
Hepatic fibrosis (6 papers, 2015 to 2024). The presence of excessive fibrous connective tissue in the liver. "These biomarkers are acetoacetyl-CoA synthetase (AACS), dipeptidyl-peptidase 4 (DPP4), d-dopachrome tautomerase (DDT), glutamine synthetase (GLUL), and glutathione S-transferase (GST); particularly, the plasma DPP4 and GST levels were highly associated with CCl4-induced liver fibrosis." (PMID 26491462, 2015).
lung carcinoma (6 papers, 2015 to 2025). "We found strong significance for a correlation between reduced survival and lower GLUL mRNA expression in both breast and lung cancer patient cohorts." (PMID 31817360, 2019). "To determine the potential upstream transcriptional factor mediated the RHPN2-induced upregulation of GLUL, we firstly examined the expression of GS and its potential transcriptional factors c-Myc, beta-catenin and YAP in a panel of lung cancer cell lines." (PMID 33552953, 2020).
Stroke (6 papers, 2016 to 2024). Sudden impairment of blood flow to a part of the brain due to occlusion or rupture of an artery to the brain. "Compared with carotid asymptomatic plaques, 2.2-fold upregulation of glutamine synthetase (GLUL) mRNA has been found in stroke-causing plaques." (PMID 36139031, 2022). "In our research, the high affinity of GLUL to galangin as its target for cerebral ischemiawas found in serum and brain tissue samples, and it was reported that the oxidative damage-induced loss of GLUL activity might be a key event in stroke-induced brain injury." (PMID 27058522, 2016).
sarcoma (5 papers, 2019 to 2025). A usually aggressive malignant neoplasm of the soft tissue or bone. "In a previous study, GLUL expression was significantly upregulated during GLN deprivation in a sarcoma model, peaking between 48 and 72 h after stress exposure, and this upregulation allowed cells to adapt and eventually resume proliferation after an initial growth arrest." (PMID 40711148, 2025).
type 2 diabetes (5 papers, 2017 to 2025). "Four core genes (COL4A2, ACACB, GLUL, and CD36) were found to be highly expressed in subcutaneous adipose tissue of obese patients accompanying type 2 diabetes." (PMID 34085602, 2021).
colon cancer (4 papers, 2001 to 2024). "In our study we have shown that the ability of colon cancer cells to compensate glutamine withdrawal by asparagine supplementation did solely depend on intracellular de novo glutamine synthesis by glutamine synthetase (GLUL)." (PMID 36032676, 2022).
coronary heart disease (4 papers, 2015 to 2021). "Genome-wide association analyses suggested that the GLUL may regulate the risk of coronary heart disease by affecting glutamate/glutamine metabolism and the activity of the γ-glutamine cycle." (PMID 33354250, 2020). "rs10911021 (a single nucleotide polymorphism present upstream of the GLUL gene) affects glutamic acid metabolism, and was shown to be associated with coronary heart disease (CHD) in patients with T2DM but a definite mechanism is unknown." (PMID 29304826, 2018). "Interestingly, a genetic variation in the region of the GLUL gene on chromosome 1q25, rs10911021, has been robustly associated with coronary heart disease among diabetic subjects in a 3-stage GWAS in 4188 type 2 diabetic patients." (PMID 26844281, 2015). "For example, a human variant of a key enzyme for glutamate turnover, the glutamate-ammonia ligase (GLUL) gene, appears to contribute to coronary heart disease risk by affecting glutamate/glutamine metabolism." (PMID 33959644, 2021).
Insulin resistance (4 papers, 2019 to 2023). Increased resistance towards insulin, that is, diminished effectiveness of insulin in reducing blood glucose levels. "The CD36, GLUL, MYH11, CD163, and COL4A2 genes were closely associated with weight loss, while the ACACB gene was closely related to insulin resistance." (PMID 34085602, 2021).
prostate carcinoma (4 papers, 2014 to 2025). A carcinoma that arises from epithelial cells of the prostate gland. "Further studies indicate that glutamine serves as both a nitrogen and carbon source in prostate cancer, with higher expression of glutamine transporters (ASCT2), GDH1, AST1, and GLUL (Glutamine synthetase)." (PMID 41179661, 2025). "We validated the expression levels of 5 prognostic genes in the TCGA-PRAD and found that both ATCAY and GLUL were lower expressed in the tumor tissues than normal prostate tissues, while the ASNS, CAD and FPGS were overexpressed in the prostate cancer group." (PMID 36983244, 2023).
acute lymphoblastic leukemia (3 papers, 2019 to 2022). Leukemia with an acute onset, characterized by the presence of lymphoblasts in the bone marrow and the peripheral blood. "Our group has previously identified reduced GLUL transcription to be associated with resistance to the chemotherapeutic agent daunorubicin in clones of acute lymphoblastic leukemia (ALL)." (PMID 31817360, 2019). "Glutamine synthetase (GLUL), is of major interest, because this enzyme may be a resistance factor in metabolic cancer treatments; like the asparaginase treatment for acute lymphoblastic leukemia (ALL) and solid cancer." (PMID 36032676, 2022).
Cerebral ischemia (3 papers, 2016 to 2023). Restriction of arterial blood supply to the brain associated with insufficient oxygenation to support the metabolic requirements of the tissue. "With the docking design to galangin, the six proteins (GLUD1, GLUL, GLS, CTH, GOT2 and HP) with high affinity might become its targets for cerebral ischemia." (PMID 27058522, 2016).
fungal infection (3 papers, 2022 to 2025). "Finally, we detected the glutamine metabolism enzymes GLS, GLS2, and GLUL mRNA expression under fungi infection in murine CD4+ T cells and CD4+ T cells obtained from CD and UC patients." (PMID 37124046, 2023).
gastric cancer (3 papers, 2018 to 2025). A primary or metastatic malignant neoplasm involving the stomach. "In gastric cancer datasets, MT2A, TXNIP, FOS, RHOB, and GLUL emerged as the five most important mRNAs to predict exmiRs." (PMID 39495117, 2024).
heart failure (3 papers, 2022 to 2025). Inability of the heart to pump blood at an adequate rate to meet tissue metabolic requirements. "We screened for differentially expressed genes in heart failure using available gene expression data from the Gene Expression Omnibus database and identified 6 important genes by a random forest classifier (ASPN, MXRA5, LUM, GLUL, CNN1, and SERPINA3)." (PMID 36254001, 2022).
leukemia (3 papers, 2016 to 2022). A malignant (clonal) hematologic disorder, involving hematopoietic stem cells and characterized by the presence of primitive or atypical myeloid or lymphoid cells in the bone marrow and the blood. "The expression level of glutamate-ammonia ligase (Glul, a gene of glutamine synthetase) was significantly up-regulated in CORT-treated small intestines, which is consistent with the previous studies which suggested that CORT could induce Glul expression in leukemia cells and also in normal tissues." (PMID 36699046, 2022).
melanoma (3 papers, 2019 to 2022). A malignant, usually aggressive tumor composed of atypical, neoplastic melanocytes. "By contrast, higher expression of metabolic genes, as well as GLUL, correlated with an improved effect on prognosis, especially for late-stage melanoma patients with metastasis." (PMID 36457136, 2022). "With regard to the genes specifically up-regulated in the MCSP CTC fraction, the majority have been involved in metastasis (LOXL4, ST6GALNAC2, PYGL), tumour growth (PLK2, CYSTM1, GLUL), and/or melanoma biology (SEC31A, WIPI1, SKP1)." (PMID 30769764, 2019). "Besides, M2-like TAMs in lung and melanoma TMEs express higher levels of glutamine metabolism enzymes, such as glutamate-ammonia ligase (GLUL), a recently uncovered mediator of the immunosuppressive and pro-metastatic properties of TAMs." (PMID 31535086, 2019).
Sepsis (3 papers, 2022 to 2025). Sepsis is defined as life-threatening organ dysfunction caused by a dysregulated host response to infection. "GLUL deficiency induces macrophage differentiation into a pro-inflammatory phenotype and exacerbates sepsis in mice." (PMID 41332909, 2025). "Thus, glutamine synthetase (GLUL) was found to be important in reducing endotoxin-induced sepsis." (PMID 39057983, 2024). "At the same time, GLUL and RPL22L1 were significantly upregulated in sepsis patients and correlated with poor prognosis." (PMID 41332909, 2025).
breast tumor (2 papers, 2011 to 2018). "Moreover, glutamine independence of breast tumor cells with a luminal phenotype was associated with elevated expression of glutamine synthetase (GLUL) and reduced glutaminase (GLS) levels." (PMID 29434187, 2018). "This concordance indicates the differential expression of GLUL, GLS and GLS2 in the luminal and basal-type cancer cell lines reflects similar systematic differences in primary breast tumors." (PMID 21852960, 2011). "In a breast tumor expression dataset, we found significantly different expression levels of GLUL, GLS and GLS2 in the corresponding luminal (luminal A and B) and basal-types of breast tumors." (PMID 21852960, 2011).
developmental and epileptic encephalopathy (2 papers, 2025 to 2026). An epilepsy associated with developmental impairment that may be due to either the underlying etiology or the superimposed epileptic activity, or both. "De novo start-loss variants in the start codon or 5′ UTR of GLUL result in abnormal glutamine synthetase stability and have been reported in nine females with developmental and epileptic encephalopathy." (PMID 39985170, 2025).
developmental delay (2 papers, 2020 to 2025). "Here, we report the first male with a pathogenic de novo variant in the same critical region of GLUL, with a phenotype of refractory focal and generalized seizures, as well as developmental delays." (PMID 39985170, 2025).
endothelial dysfunction (2 papers, 2013 to 2025). In vascular diseases, endothelial dysfunction is a systemic pathological state of the endothelium (the inner lining of blood vessels) and can be broadly defined as an imbalance between vasodilating and vasoconstricting substances produced by (or acting on) the endothelium. "Specifically, GLUL may contribute to CHD through its involvement in glutamate metabolism and endothelial dysfunction, while SERPINA1 appears to be linked to protease inhibition and inflammation modulation." (PMID 41287052, 2025).
hepatoblastoma (2 papers, 2021 to 2024). Hepatoblastoma (HB) is a malignant hepatic tumor and is the most common pediatric liver cancer. "In hepatoblastoma, high GLUL expression is associated with higher median overall survival, explained by the specific tumorigenesis pathway which includes the development of a more differentiated, prognostic favorable fetal subtype with high GLUL and GS expression." (PMID 34235580, 2021). "Hepatoblastoma samples exhibited strong GLUL expression and glutamine synthesis, generally as a result of CTNNB1 mutations." (PMID 39684755, 2024). "Interestingly, although C1 and C2 HB significantly differ for GLUL expression, the C1 group also includes 12.5% tumors with low GLUL expression, and vice versa, the C2 group includes 37.5% hepatoblastomas with high GLUL expression." (PMID 34235580, 2021). "Independent of mutations and histology, hepatoblastoma samples showed strong GLUL expression and glutamine synthesis." (PMID 34235580, 2021). "In amino acid biosynthesis, GLUL and ASNS have been shown to correlate with overall survival during hepatoblastoma." (PMID 39684755, 2024). "We examined GLUL and ASNS expression by RT-qPCR and by Western blot analysis in the embryonal cell lines Huh-6 and HepT1, and in five hepatoblastoma specimens." (PMID 34235580, 2021).
Lewis lung carcinoma (2 papers, 2022 to 2023). "Corroborating these decisions, TAMs from Lewis lung carcinoma, which exhibit M2 phenotype, also revealed elevated gene expression of glutamine pyruvate transaminase (GPT) and glutamate-ammonia ligase (GLUL)." (PMID 35093033, 2022).
nasopharyngeal carcinoma (2 papers, 2022 to 2023). A carcinoma arising from the nasopharyngeal epithelium. "GLUL is a potential downstream target of miR-183-5p, and OIP5-AS1 enhances cell motility through the upregulation of GLUL by targeting miR-183-5p in nasopharyngeal carcinoma cells." (PMID 36499136, 2022). "GLUL was found to be related to OIP5-AS1-mediated tumor promotion in nasopharyngeal carcinoma cells." (PMID 36499136, 2022).
psoriasis (2 papers, 2015 to 2017). An autoimmune condition characterized by red, well-delineated plaques with silvery scales that are usually on the extensor surfaces and scalp. "Of the most psoriasis-specific DEGPs, the majority were induced by IL-17A (e.g., FERMT1, GLUL, SULT2B1); in contrast, the most non-specific DEGPs were not disproportionately induced by IL-17A and several were repressed (e.g., AKR1B10, RNF213, ISG15)." (PMID 26251673, 2015).
triple-negative breast carcinoma (2 papers, 2019 to 2021). An invasive breast carcinoma which is negative for expression of estrogen receptor (ER), progesterone receptor (PR), and human epidermal growth factor receptor 2 (HER2). "Triple negative breast cancer (TNBC), for example, expresses low levels of glutamine synthetase (GLUL, glutamate-ammonia ligase)." (PMID 34631530, 2021). "We examined GLUL protein levels by western blotting in a panel of cancer cell lines, including A549, H1299, H460 (NSCLC), HeLa (cervical cancer), HCC1954 (breast ductal carcinoma), MDA-MB-231 (triple-negative breast cancer—TNBC)." (PMID 31817360, 2019).
brain malformations (1 paper, 2023). "Also, the mutation in GLUL was related to brain malformations in neonates." (PMID 37016705, 2023).
Cachexia (1 paper, 2021). Severe weight loss, wasting of muscle, loss of appetite, and general debility related to a chronic disease. "A total of 340 genes from muscle, including several known genes for cachexia such as FOXO1, FOXO3, PIK3RI, GLUL were correlated with CWLG." (PMID 33923976, 2021).
deafness (1 paper, 2024). An inherited or acquired condition characterized by the complete loss of the ability to hear from one or both ears. "In conclusion, our study highlights the necessity of glula and glulb for hair cell development and function, providing new targets for the clinical treatment of patients with deafness and balance defects caused by GLUL alterations." (PMID 39519113, 2024).
ependymoma (1 paper, 2023). A WHO grade II, slow growing tumor of children and young adults, usually located intraventricularly. "However, normal glial cells and glia-like tumor cells have their specific lineage-associated genes, such as FABP7 and MSX1 in normal ASCs, OLIG2 and OPCML in normal OPCs and OLs, FRMD5 in ASC-like ependymomas and GLUL in OPC/OL-like ependymomas." (PMID 37095395, 2023).
focal epilepsies (1 paper, 2025). "For example, in the GluN cluster of patients with FCDII, we observed downregulation of GRIN1 and PRRT2, two genes causing monogenic forms of focal epilepsies, and upregulation of GLUL, pointing toward alterations of the glutamate signaling and neurotransmission in glutamatergic neurons." (PMID 40307383, 2025).
liver cirrhosis (1 paper, 2019). "For example, liver cirrhosis results in decreased expression of GLUL and the urea cycle enzyme CPS1." (PMID 31366360, 2019). "Previous research has shown that there was an 80% reduction in GLUL activity and a 30% reduction in CPS1 activity in a rat model of liver cirrhosis." (PMID 31366360, 2019). "We recognize that liver cirrhosis is a complex disease with many changes besides altered CPS1 and GLUL activity, so this model is a simplified representation of liver cirrhosis." (PMID 31366360, 2019).
mouth ulcers (1 paper, 2023). "The proteins encoded by eight genes (PMEL, ARFIP1, FAM213A, GLUL, CADM2, FAIM3, RIPK2, and DECR1) have only one SNP instrumental variable and have a association with mouth ulcers using the Wald ratio method." (PMID 37369724, 2023).
non-small cell lung carcinoma (1 paper, 2021). A group of at least three distinct histological types of lung cancer, including non-small cell squamous cell carcinoma, adenocarcinoma, and large cell carcinoma. "In addition, GLUL mRNA level, but not GLS1, is increased in KRAS mutated non-small cell lung cancer (NSCLC) compared to wild-type." (PMID 33567690, 2021).
osteoporosis (1 paper, 2025). A condition of reduced bone mass, with decreased cortical thickness and a decrease in the number and size of the trabeculae of cancellous bone (but normal chemical composition), resulting in increased fracture incidence. "However, GLUL expression was downregulated in the BMSCs of elderly patients with osteoporosis (SOP)." (PMID 40646162, 2025).
Pancytopenia (1 paper, 2017). An abnormal reduction in numbers of all blood cell types (red blood cells, white blood cells, and platelets). "Most of the genes from day 1 appeared 2-fold downregulated (e.g., CDCA7L or GBP2), but three were 3–5-fold upregulated (C11orf96, GLUL, TM4SF19) relative to H0 when developing a HARS without pancytopenia." (PMID 28236054, 2017).
postmenopausal osteoporosis (1 paper, 2025). Metabolic disorder associated with fractures of the femoral neck, vertebrae, and distal forearm. "That is, GLUL was upregulated in a postmenopausal osteoporosis animal model." (PMID 40646162, 2025).